ITGB3 (integrin subunit beta 3)
Diseases named in the same sentence as ITGB3 in open-access papers (continued):
Sharing a sentence is not in itself a finding about the gene and the disease.
endometriosis (10 papers, 2020 to 2025). The growth of functional endometrial tissue in anatomic sites outside the uterine body. "Khorram and Lessey associated decreased expression levels of ITGA5/ITGB3 integrin during the WOI in endometriosis women with an unfavourable environment for embryo implantation." (PMID 32474803, 2020). "Integrin β3 (ITGB3) is upregulated in ectopic endometrial stromal cells from endometriosis patients, promoting cell proliferation and invasion." (PMID 40508002, 2025). "ITCH, a ubiquitin E3 ligase involved in endometriosis, is downregulated in this condition and, when overexpressed, enhances the ubiquitination of ITGB3, affecting the proliferation and invasion capabilities of ectopic cells." (PMID 40508002, 2025). "Our prior study indicated that in the ectopic endometrium of women with endometriosis, downregulation of lncRNA H19 inhibits the proliferative and invasive abilities of stromal cells through modulation of miR-124-3p and ITGB3 expression." (PMID 33656053, 2021). "The opposing expressions of ITCH and ITGB3 suggest that dysregulation of the ubiquitin process may play a crucial role in endometriosis pathogenesis." (PMID 40508002, 2025). "Inhibition of ITGB3 expression can upregulate miR-124-3p and downregulate the expression of lncRNA-H19, thereby inhibiting the proliferation and invasion of ectopic endometrial cells and providing a new target for the treatment of endometriosis." (PMID 33550277, 2021). "In baboon models of endometriosis, a significantly reduced endometrial expression of HOXA10 and integrin β3 (ITGB3), which are known to be involved in endometrial receptivity, has been reported one year after the induction of endometriosis." (PMID 36830705, 2023). "H19 has been shown to regulate several pathways that are important in endometriosis, IGF1R, ITGB3, IER3, and ACTA2." (PMID 36232884, 2022).
autism (9 papers, 2009 to 2023). Persistent deficits in social interaction and communication and interaction as well as a markedly restricted repertoire of activity and interest as well as repetitive patterns of behavior. "Our results point to a cell-specific requirement for Itgb3, an autism risk gene, in establishing a normal gradient of dendritic complexity and spine density in excitatory pyramidal neurons across the developing mouse cerebral cortex." (PMID 33317577, 2020). "Overall, our observations support the idea that Itgb3, an autism risk gene, has an essential, cell-specific function in establishing an anatomical gradient among excitatory neurons of the living cerebral cortex." (PMID 33317577, 2020). "Volume differences in several mouse models related to both autism and the 5-HT system have been examined previously, including an Itgb3 KO, which encodes a SERT-binding partner." (PMID 29651330, 2018). "ITGB3 is known as an autism-susceptible gene, which was identified as a male quantitative trait locus for whole blood serotonin levels." (PMID 21935445, 2011). "Thus, the autism susceptibility gene Itgb3 is required for establishing a tangential pattern of basal dendritic complexity among layer II/III cortical pyramidal neurons, suggesting an early role for this molecule in the developing brain." (PMID 33317577, 2020). "Another SNP, rs5918 located within ITGB3, has been shown to be associated with autism in both sexes but with different risk effect, which could explain the difference of reproducibility observed in males and females." (PMID 22017886, 2011). "5-HTTLRP is associated with the presence of aggressiveness and ADHD in males only and MAOA is located on the X chromosome, whereas the Leu33 allele in ITGB3 has been suggested to have a dominant effect in males and a recessive effect in females, as far as it concerns association to autism." (PMID 19949574, 2009). "show that enhancing expression of the autism gene Itgb3 by CRISPR activation rebalances neuronal network activity by normalizing signaling of the metabotropic glutamate receptor mGluR5." (PMID 36035754, 2022). "This is consistent with several previously published mouse models related to autism, including Chd8+/−, 22q11.2, Fmr1, Itgb3, En2, Nrxn1a, and Shank3." (PMID 33757588, 2021). "ITGB3 has been reported to show genetic and expression interaction with SLC6A4, leading to increase of autism susceptibility." (PMID 19949574, 2009). "Accordingly, Itgb3 knockout (KO) mice exhibit autism-like phenotypes." (PMID 36035754, 2022). "We confirmed several loci responsible for Autism and Pervasive Developmental Disease including MACROD2, ITGB3, CADM2, and GRIK2." (PMID 25477900, 2014).
bleeding disorder (9 papers, 2013 to 2023). "GT is caused by mutations in the genes encoding ITGA2B or ITGB3 that result in qualitative or quantitative abnormalities in the platelet membrane proteins leading to bleeding disorders." (PMID 26096001, 2016).
breast tumor (9 papers, 2012 to 2024). "In addition to preventing breast tumor beginning cells from self-renewing, overexpression of miRNA30 can also prevent the expression of the target gene ITGB3, which causes apoptosis in breast tumor–initiating cells." (PMID 39742357, 2024). "On the contrary, it has been shown that miR-30 can inhibit the self-renewal and induce apoptosis of breast tumor-initiating cells (BT-ICs) by silencing Ubc9 and ITGB3." (PMID 25170877, 2014). "Moreover, ITGB3 silencing with shRNA reduced tumourigenesis in vitro and in vivo, suggesting that ITGB3 is a candidate therapeutic target for most aggressive breast tumours able to survive under low-oxygen conditions." (PMID 29383126, 2017). "Therefore, the expression change of ITGB3 was detected in ICJ exposed primary breast tumors." (PMID 27374079, 2016).
Macrothrombocytopenia (8 papers, 2013 to 2026). "The αIIbArg995‐to‐Trp mutation is the most common mutation type of ITGA2B/ITGB3‐related macrothrombocytopenia in Japan." (PMID 41503871, 2026). "While classical GT typically exhibits normal platelet counts and morphology, very rare mutations in ITGA2B (encoding αIIb) and/or ITGB3 (encoding β3) cause macrothrombocytopenia or increased platelet anisotropy (heterogeneity of platelet size and morphology)." (PMID 41503871, 2026). "For over two decades, cases of mutations in ITGA2B or ITGB3 accompanied by spontaneous activation of αIIbβ3 and macrothrombocytopenia have been reported in clinical practice." (PMID 41503871, 2026). "Current research suggests that gain‐of‐function mutations in ITGA2B or ITGB3 underlie the pathogenesis of most ITGA2B/ITGB3‐related macrothrombocytopenia and mechanistically distinguish it from classical GT." (PMID 41503871, 2026). "However, recent reports have documented non‐activating ITGB3 mutations that also cause macrothrombocytopenia, presenting a profound challenge to the mechanistic understanding of ITGA2B/ITGB3‐related macrothrombocytopenia." (PMID 41503871, 2026). "This review summarises the reported cases of gain‐of‐function mutations in ITGA2B and ITGB3 associated with ITGA2B/ITGB3‐related macrothrombocytopenia hitherto and discusses the potential molecular pathways contributing to the unique phenotypes in ITGA2B/ITGB3‐related macrothrombocytopenia." (PMID 41503871, 2026). "This provided the first evidence that a non‐activating ITGB3 mutation could lead to macrothrombocytopenia." (PMID 41503871, 2026). "Ultimately, these efforts will enable precision therapeutic targeting based on mutational profiles, thereby improving clinical management of ITGA2B/ITGB3‐related macrothrombocytopenia." (PMID 41503871, 2026). "Although functional assays to evaluate spontaneous activation of integrin αIIbβ3 were not conducted, the current evidence supports the diagnosis of ITGA2B/ITGB3‐related macrothrombocytopenia." (PMID 41503871, 2026). "This particular type of disorder is called ITGA2B/ITGB3‐related macrothrombocytopenia and has been considered a subset of congenital macrothrombocytopenia." (PMID 41503871, 2026). "Although the two types of αIIbβ3 mutations downregulate RhoA through different molecular mechanisms, targeted modulation of the RhoA/ROCK pathway may represent a therapeutic strategy for ITGA2B/ITGB3‐related macrothrombocytopenia." (PMID 41503871, 2026). "Consequences of variants in ITGA2B and ITGB3 in GT patients were reported to cause lack of function, prevention of αIIbβ3 expression, and are associated with activated integrin defects and macrothrombocytopenia." (PMID 30792900, 2019). "MYH9-RD, mono and biallelic BSS and ITGA2B/ITGB3-RT are currently classified as inherited macrothrombocytopenias, while ANKRD26-RT has been reported to have platelets of normal size." (PMID 23617394, 2013). "In the macrothrombocytopenia group, case No. 24 had a heterozygous VUS ITGB3, and case Nos." (PMID 40941697, 2025).
prostate carcinoma (8 papers, 2015 to 2024). A carcinoma that arises from epithelial cells of the prostate gland. "In good accordance, it has been shown that transmembranous shifting of the integrin subtype β1 (ITGB1) may contribute to metastatic progression of bladder cancer cells, and ITGB3 translocation has been associated with adhesive behaviour in prostate cancer cells." (PMID 29721158, 2018). "Previous literature indicated that these six genes, i.e., CAV1, COL4A2, HSPB1, ITGB3, MAP1A and MCAM, were linked to prostate cancer progression." (PMID 26158290, 2015). "A core network consisting of 19 genes was identified, and most genes in the core network have been reported to play important roles in prostate cancer, especially TPM1, ITGB3, and CALD1." (PMID 38778150, 2024). "Network analysis was performed on the intersection of 300 genes from these six datasets, and qRT-PCR validation confirmed the 3 top hub genes (TPM1, ITGB3, and CALD1) in the network are expression in prostate cancer tissues." (PMID 38778150, 2024). "In this study, we selected six genes, that had additionally been independently reported to be related to prostate cancer progression, CAV1, COL4A2, HSPB1, ITGB3, MAP1A and MCAM." (PMID 26158290, 2015). "We compared the expression levels of eight integrin subunits (ITGA2, ITGA5, ITGAV, ITGB1, ITGB3, ITGB4, ITGB5, and ITGB6), HOXB13, HOXA11-AS, CCL2, CXCL12, and IBSP in prostate cancer tissues that had metastasized to bone, lymph nodes, lungs, liver, and other organs." (PMID 33514011, 2021).
glioblastoma (6 papers, 2016 to 2024). The most malignant astrocytic tumor (WHO grade IV). "U-251MG is a glioblastoma cell line in which ITGB3 is distributed both in the nucleus and cytoplasm, mainly in the cytoplasm." (PMID 38814534, 2024). "ITGB3 has been reported to be recruited to the membrane and to regulate invasion in hypoxia in glioblastoma by interacting with type III EGF receptor (EGFRvIII) in a hypoxic microenvironment enriched with vitronectin." (PMID 29383126, 2017). "Cilengitide is an antagonist of integrins and preliminary but promising results have suggested that the microenvironment plays a role in glioblastoma progression and that ITGB3 inhibitors can act in a neoadjuvant setting to prevent metastasis rather than reduce tumours once formed." (PMID 29383126, 2017).
osteosarcoma (6 papers, 2019 to 2025). A usually aggressive malignant bone-forming mesenchymal neoplasm, predominantly affecting adolescents and young adults. "To elucidate the underlying mechanism of the anti‐cisplatin effect of ITGB3 in osteosarcoma, we collected total RNA and performed transcriptome analysis on 143B (WT), ITGB3‐KO (KO), cisplatin‐treated 143B (Cis_WT) and ITGB3‐KO (Cis_KO) cells." (PMID 36772869, 2023). "Since ITGB3 has an obvious causal or prognostic effect on osteosarcoma recurrence, we collected 18 paired osteosarcoma tissues (primary: n = 9, recurrence: n = 9) and detected the expression level of ITGB3 by IHC staining assays." (PMID 36772869, 2023). "First, using a clinical database and clinical samples, we found that ITGB3 was more highly expressed in recurrent osteosarcoma patients and was associated with tumor proliferation." (PMID 36772869, 2023). "Additionally, ITGB3 expression has been associated with increased cisplatin resistance in osteosarcoma." (PMID 40410897, 2025). "While our findings establish targeting ITGB3 as a radiosensitizing strategy in preclinical osteosarcoma models, three key limitations merit discussion." (PMID 40410897, 2025). "Through integrative analysis involving RNA-seq screening, literature curation, expression validation, and functional characterization, we identified ITGB3 as a putative radiosensitization target in osteosarcoma." (PMID 40410897, 2025). "Quantitative assessment of osteogenic markers (RUNX2, OCN, and OPN) confirmed that ITGB3-KD drives osteogenic differentiation in osteosarcoma." (PMID 40410897, 2025). "We comprehensively validated the radiosensitizing effect of ITGB3-KD on osteosarcoma cells in vitro by performing assays for cell viability, proliferation, apoptosis, migration, and invasion." (PMID 40410897, 2025). "Taken together, these findings indicate that ITGB3-KD exerts radiosensitizing effects on osteosarcoma cells by promoting osteogenic differentiation and apoptosis through activation of the JNK/c-JUN/RUNX2 pathway." (PMID 40410897, 2025). "The results presented above initially suggested the potential of ITGB3-KD to radiosensitize osteosarcoma cells." (PMID 40410897, 2025). "Using HOS human osteosarcoma cells transfected with ITGB3-KD and ITGB3-NC lentiviruses, we constructed BALB/c nude mouse models of subcutaneous tumors in the inguinal region and orthotopic tumors in the tibia for in vivo efficacy and mechanistic validation." (PMID 40410897, 2025). "The radiosensitizing effect of ITGB3-knockdown (KD) was subsequently validated in both in vitro and in vivo osteosarcoma models." (PMID 40410897, 2025). "ITGB3-KD had a radiosensitizing effect on osteosarcoma in vitro by inhibiting cell viability, proliferation, migration, and invasion and promoting apoptosis." (PMID 40410897, 2025). "In the present study, ITGB3 was initially identified as a target that modulates the radiosensitivity of osteosarcoma through RNA sequencing (RNA-seq)." (PMID 40410897, 2025). "Culture in osteogenic differentiation medium promoted osteosarcoma radiosensitization by enhancing the osteogenic differentiation status, working synergistically with ITGB3-KD." (PMID 40410897, 2025). "These western blot findings suggested that ITGB3-KD enhanced osteogenic differentiation in osteosarcoma by activating the JNK/c-JUN pathway, with RUNX2 serving as the major downstream molecule mediating this effect." (PMID 40410897, 2025). "The findings suggest that ITGB3-KD enhances the radiosensitivity of osteosarcoma cells by promoting osteogenic differentiation and apoptosis via activation of the JNK/c-JUN/RUNX2 signaling pathway." (PMID 40410897, 2025). "This study demonstrates the radiosensitizing effect of ITGB3-KD on osteosarcoma both in vitro and in vivo." (PMID 40410897, 2025). "ITGB3 promotes cisplatin resistance in osteosarcoma and is abundant in both drug resistance and the mesenchymal status of mesenchymal lung cancer." (PMID 38814534, 2024).
osteosarcoma (continued). "In the present work, ITGB3 was identified as a potential regulator of tumorigenicity and cisplatin resistance in osteosarcoma through public clinical dataset (TARGET database) analysis, clinical sample detection, and functional experimental model testing." (PMID 36772869, 2023). "In the present work, ITGB3 knockout osteosarcoma cells had the decreased proliferation and migration ability, increased apoptosis and slowing cell cycle progression in vitro, and reduced cisplatin resistance in vivo." (PMID 36772869, 2023). "In conclusion, a thorough investigation of the molecular mechanism by which ITGB3 participates in osteosarcoma cisplatin resistance via the involvement of the signaling pathway should promote treatment effects." (PMID 36772869, 2023). "To investigate the mechanism by which ITGB3 exerts cisplatin resistance in osteosarcoma, we analyzed the genes that were only upregulated and downregulated in the Cis_KO group using the computational tool Cytoscape and STRING enrichment analysis." (PMID 36772869, 2023). "To summarize, ITGB3 expression was positively related to increased cisplatin resistance and decreased apoptosis in osteosarcoma progression." (PMID 36772869, 2023). "The ratios of ITGB3‐positive (ITGB3+), Ki67‐positive (Ki67+), and ITGB3+/Ki67+ double‐positive osteosarcoma cells in the recurrence groups were significantly higher than those in the primary groups, which was in agreement with our prediction." (PMID 36772869, 2023). "Accordingly, ITGB3 performed the functions of proliferation and cisplatin resistance in osteosarcoma through the MAPK and VEGF signaling pathways." (PMID 36772869, 2023). "We then tested the functions of ITGB3 in the cisplatin resistance of osteosarcoma cells by using CCK‐8 assays and 143B cell knockout for ITGB3." (PMID 36772869, 2023). "In osteosarcoma, ITGB3 performed the functions of proliferation and cisplatin resistance through the MAPK and VEGF signaling pathways." (PMID 37760946, 2023). "ITGB3 was identified as a potential regulator of tumorigenicity and cisplatin resistance in relapsed osteosarcoma." (PMID 36772869, 2023). "In this research, we detected the relationship between ITGB3 and the clinical characteristics of patients and analyzed the expression of ITGB3 in human osteosarcoma tissues." (PMID 36772869, 2023). "Our results will contribute to a better understanding of the function and mechanism of ITGB3 in osteosarcoma cisplatin resistance and provide a novel therapeutic target to decrease cisplatin resistance and tumor recurrence in osteosarcoma patients." (PMID 36772869, 2023). "On the basis of the research background regarding the role of ITGB3 in regulating osteogenic differentiation, we hypothesize that ITGB3 may influence the radiosensitivity of osteosarcoma by modulating osteogenic differentiation." (PMID 40410897, 2025). "Furthermore, when ITGB3-KD was synergistically combined with conditions that promote osteogenic differentiation, the radiosensitizing effect on osteosarcoma cells was notably potentiated." (PMID 40410897, 2025). "Furthermore, both subcutaneous and orthotopic tibial tumor models revealed the radiosensitizing effect of ITGB3-KD on osteosarcoma in vivo." (PMID 40410897, 2025). "This study aimed to explore the efficacy of ITGB3 as a novel radiosensitizing target in osteosarcoma and to explore whether the modulation of osteogenic differentiation plays a role in mediating the radiosensitizing effect." (PMID 40410897, 2025). "ITGB3-KD radiosensitized osteosarcoma in vivo in subcutaneous and orthotopic tibial tumor models." (PMID 40410897, 2025). "On the basis of these observations, our subsequent research efforts will focus on elucidating the regulatory role of ITGB3 knockdown in osteogenic differentiation and comprehensively characterizing the role of osteogenic differentiation in the radiosensitization of osteosarcoma." (PMID 40410897, 2025).